APOBEC3B (apolipoprotein B mRNA editing enzyme catalytic subunit 3B)
Diseases named in the same sentence as APOBEC3B in open-access papers (continued):
Sharing a sentence is not in itself a finding about the gene and the disease.
tumor (continued). "In our previous study, differences in survival were observed in patients with metastatic bladder cancer based on APOBEC3B expression, and a potential relation with tumor-infiltrating lymphocytes was proposed." (PMID 38827321, 2024). "A significant and positive correlation of gene expression was found between UNG and APOBEC3B in both tumor subtypes (LAS: R=0.33 and P=8.8e-04; HAS: R=0.45 and P=1.5e-05), but not between UNG and APOBEC3A (LAS: R=-0.094 and P=0.36; HAS: R=0.046 and P=0.67)." (PMID 38617360, 2024). "Genes like APOBEC3B, APOBEC3C, and YTHDC1, highly expressed in tumor cells, were linked to tumor stemness and correlated with markers such as SOX2 and BM1." (PMID 39409886, 2024). "There was a significant association between APOBEC3B and ATR expression in the tumor tissues obtained from patients with MIBC." (PMID 38827321, 2024). "Here we report a murine model that expresses tumor-like levels of human APOBEC3B after Cre-mediated recombination." (PMID 36865194, 2023). "Recent murine studies have established cause-and-effect relationships, with both human APOBEC3A and APOBEC3B proving capable of promoting tumor formation in vivo." (PMID 37298259, 2023). "Cycling hypoxia was also shown to promote replication catastrophe in tumor cells and enhance the expression and activity of APOBEC3B (apolipoprotein B mRNA-editing catalytic polypeptide) deaminase, which is involved in tumor mutagenesis." (PMID 36831579, 2023). "APOBEC3B mRNA and protein levels were higher in tumour samples from Grade III stage in comparison to Grade I or Grade II stage and correlated to poor prognosis." (PMID 37568604, 2023). "Among the gene expressions, it was found that the expression of APOBEC3A and APOBEC3B was significantly higher in tumor tissues than in normal tissues." (PMID 35510248, 2022). "APOBEC3B proved to be highly expressed in most tumor tissues, but weakly in a few types, such as COAD, LAML, READ, THCA, and THYM." (PMID 35918642, 2022). "Based on the bio-information analysis, the transcriptional level of APOBEC3G was dramatically increased in AML compared to the control cohort, which is contrary to another tumor-related gene member APOBEC3B." (PMID 36144542, 2022). "We then obtained the top 100 genes related to APOBEC3B expression based on all tumor expression data of TCGA using the GEPIA2 tool." (PMID 35918642, 2022). "The results of IHC analysis showed that APOBEC3B protein expression was upregulated in UTUC tumor tissues, with a positive rate of 93.59% (73 out of 78 tissues)." (PMID 35903294, 2022). "Wang found that APOBEC3B can promote the growth of liver tumor cells through the NF-κB signaling pathway, promote the recruitment of tumor macrophages, and increase the CD8 + T-expressing myeloid-derived suppressor cells and PD1." (PMID 36419192, 2022). "The expression of APOBEC3B and E6 was compared in terms of pathological T stage, pathological N stage, tumor grade, and LVI by linear regression analysis." (PMID 35903294, 2022). "Inhibiting APOBEC3B via modified single-stranded DNA and thereby reducing the risk of genomic mutations and targeting uracil DNA glycosylases to selectively inhibit tumor cells with high APOBEC3B expression have been described as possible strategies." (PMID 35592333, 2022). "APOBEC3A expression level was similar between the 2 sample sources, but the APOBEC3B expression level was higher in frozen tumor tissue than in the FFPE sample." (PMID 35592333, 2022). "APOBEC3B is widely expressed at low levels in a variety of normal tissues and organs, but it is significantly upregulated in different types of tumor tissues and tumor lines." (PMID 36203448, 2022). "We analyzed the gene alteration status of APOBEC3B in all tumor samples in the TCGA dataset through cBioPortal." (PMID 35918642, 2022). "The expression of APOBEC3B was evaluated in different tumor types and adjacent normal tissues using the TIMER database." (PMID 36249021, 2022).
tumor (continued). "As a mimic of the clinical scenario in which a patient’s own tumor cells would be used as the platform for the APOBEC3B-modified vaccine, Mel888-APOBEC3BACTIVE or Mel888-GFP cells were used to educate donor T cells against unmodified Mel888 cells." (PMID 32034147, 2020). "Together, these data show that APOBEC3B-modification enhances the immunogenicity of human tumor cells for T-cell recognition and that such an approach can potentially be translated clinically in the context of an autologous vaccine platform." (PMID 32034147, 2020). "In our cohort, we found that ACC tumor samples with a high APOBEC3B expression had a higher number of chromosomal gain/loss particularly in chromosome 4 and 8 as compared to tumor samples with a low APOBEC3B expression, suggesting that it may have a role in chromosomal instability." (PMID 32934779, 2020). "Therefore, we tested here the controversial concept that instead of preventing ongoing mutation in tumor cells, actively driving a high mutational load through APOBEC3B expression may enhance therapy by rendering poorly immunogenic tumors susceptible to immunotherapy." (PMID 32034147, 2020). "In addition, the concept of direct transfer of APOBEC3B into live tumor cells to induce immunogenicity through formation of novel heteroclitic neo-epitopes cannot yet be considered as a clinical option due to the risks of inducing further tumor promoting mutations." (PMID 32034147, 2020). "We found the expected associations between the APOBEC3B deletion and decreased levels of APOBEC3B expression in both tumor and normal tissue, validating SNP rs12628403 as a proxy for APOBEC3B deletion." (PMID 31856876, 2019). "Several studies showed that the expression levels of APOBEC3B in tumor tissue were higher compared with normal tissue." (PMID 30093965, 2018). "Some studies suggested a potential role of APOBEC mutagenesis in tumor resistance to therapy, with a possible resistance mechanism explained by increased tumor heterogeneity when APOBEC3B activity is elevated." (PMID 29642934, 2018). "Despite these limitations, we observed a number of correlations, e.g., those between APOBEC3A and APOBEC3B expression levels, that have also been reported in patient tumor samples." (PMID 29642934, 2018). "17-AAG acts in a variety of tumor types, and sensitivity to this agent was also correlated with APOBEC3B in an earlier analysis of RNA-seq gene expression in the CCLE and GDSC cell lines by Cescon and Haibe-Kains." (PMID 29642934, 2018). "Future in-depth research is demanded to understand APOBEC3B protein regulation and the potential interaction with many other oncogenes and tumor suppressors." (PMID 28572915, 2017). "This implies a role for APOBEC3B not only at the stage of the primary tumor but also, and according to our data even more dominantly, during tumor evolution of metastatic breast cancer." (PMID 28141868, 2017). "The effect of PRIMPOL on mutations at TpC dinucleotides was strongest for C transversions (TpC>G, TpC>A), which is in line with anti-mutagenic activity of PRIMPOL in response to AP-sites generated by APOBEC3B in these tumours." (PMID 26926109, 2016). "APOBEC3B mRNA expression is upregulated in multiple tumor types and this has been shown to correlate with an increased mutational load, particularly an increase in C>T transversions." (PMID 27552096, 2016). "Because APOBEC3B is an endogenous and likely stochastic mutagen, it is predicted to drive tumor evolution and contribute to all processes attributable to mutations (that is, tumor development, progression, heterogeneity, metastasis, and drug resistance)." (PMID 25848704, 2015). "Only one family member, APOBEC3B, was expressed at significantly higher levels in tumor tissues in comparison with matched normal tissues, and it was barely detectable in normal breast tissues." (PMID 25848704, 2015).
tumor (continued). "Our results indeed show that patients with high APOBEC3B mRNA levels in their primary tumor more rapidly experience disease relapse." (PMID 25123150, 2014). "Long-lived APOBEC3B-high tumor cells, even when still dormant, will have more opportunities to accumulate mutations, evolve, escape the dormant state, outgrow, metastasize, and potentially acquire resistance during additional rounds of therapy." (PMID 25123150, 2014). "And the expression levels of APOBEC3A and APOBEC3B were significantly lower in tumor tissues than in morphologically normal operative margin tissues." (PMID 25502777, 2014). "In this cohort, mRNA expression of APOBEC3B was positively correlated with nodal status (P = .009), tumor size (P < .001), and grade (P < .001) and negatively with both ER (P < .001) and PR (P < .001)." (PMID 25123150, 2014). "DNA cytosine deaminase APOBEC3B (A3B) is one of the endogenous sources of somatic mutations in many types of human cancers and is associated with tumor progression rather than tumorigenesis." (PMID 40213992, 2025). "Indeed, depending on the level, duration, and model system, the expression of APOBEC3B can lead to various outcomes, including that of there being no overt tumor phenotypes, increased tumor rates, detriments to tumor development, or lethality." (PMID 38254863, 2024). "Additional genes involved in the BER pathway exhibited a similar pattern, with positive association with APOBEC3B but not APOBEC3A in tumor samples." (PMID 38617360, 2024). "Daniela's recent study found that the typical and atypical nuclear factor-kappa B (NF-κB) pathway could mediate the high expression of APOBEC3B in immune or tumor cells." (PMID 39844908, 2024). "However, a subsequent study found that the constitutive, ubiquitous expression of higher and human tumor-like APOBEC3B levels from CAG the promoter accelerates liver and lymphoma cancer formation as well as metastasis in non-predisposed animals." (PMID 38254863, 2024). "Notably, the squamous-differentiated area of the tumor was determined to be almost unstained with the APOBEC3B antibody." (PMID 38827321, 2024). "Identification of the viral proteins involved could be used to design better oncolytic vectors capable of propagating in tumor cells expressing high levels of APOBEC3B." (PMID 36745676, 2023). "Here, we report a murine model that expresses tumor-like levels of human APOBEC3B." (PMID 37797615, 2023). "Nevertheless, the host cell may have expressed APOBEC3B during initial MCPyV infection or earlier in tumor development before the tumor removal, because APOBEC expression is naturally episodic and fluctuating." (PMID 36970060, 2022). "We further analyzed the relativity between one-class logistic regression (OCLR) and APOBEC3B gene expression, and our results revealed that tumor tissues with APOBEC3B high expression have higher stemness, which evaluates the proliferative activity and malignant potential of tumor cells." (PMID 36249021, 2022). "Additionally, the APOBEC3B expression level was higher than that of APOBEC3A in most frozen tumor tissue samples." (PMID 35592333, 2022). "We reasoned that the aggressive nature ofthe KP model did not allow sufficient time for APOBEC3B to induce mutationsduring tumour development, leading to only a few detectable SNVs with lowallelic frequency." (PMID 35930804, 2022). "We assessed intra-tumoral and peri-tumoral TILs, but not tumor mutation burden, in relation to APOBEC3B expression." (PMID 33925044, 2021). "Therefore, in the present study, we investigated the prognosis of metastatic urothelial carcinoma according to APOBEC3B expression and analyzed tumor-infiltrating lymphocytes (TILs) by investigating tumor immunity." (PMID 33925044, 2021). "Additionally, we observed a significant correlation between APOBEC3B gene expression level and the overall tumor burden in ACC tumor samples from the TCGA dataset." (PMID 32934779, 2020).
tumor (continued). "Analyzing the 4-nucleotide context of 788 WGSs from 27 tumor types with evidence of APOBEC activity enrolled within the PCAWG ICGC consortium, we observed a strong positive association between APOBEC3A/APOBEC3B ratio and APOBEC mutational burden (linear regression p < 0.0001)." (PMID 32317634, 2020). "Finally, and also consistent with our murine data, we confirmed that the use of APOBEC3B modification to stimulate human antitumor T-cell responses was applicable across tumor types." (PMID 32034147, 2020). "This hypothesis is consistent with data showing that APOBEC3B expression correlates with increased frequency of tumor infiltrating lymphocytes." (PMID 32034147, 2020). "Interestingly, this signature was associated with high tumor mutational burden (TMB) and high expression levels of APOBEC3B and interferon inducible genes." (PMID 33049910, 2020). "In addition, previous studies demonstrated a relation between increased APOBEC3B enzymatic activity and tumor grade." (PMID 31349863, 2019). "Tumor transcriptome analyses support involvement of the RB pathway in APOBEC3B regulation." (PMID 30723127, 2019). "Since APOBEC3B is related to tumor proliferation (Ki-67 labelling index), tumors with high APOBEC3B expression might be sensitive to chemotherapy." (PMID 30093965, 2018). "Importantly, we encountered a significant increase in APOBEC3B mRNA levels in the metastases compared to their corresponding primary tumor." (PMID 28141868, 2017). "However, regarding ER-negative primary tumors, only loco-regional lymph node metastases showed increased APOBEC3B expression when compared to the corresponding primary tumor (P = 0.028)." (PMID 28141868, 2017). "We found that APOBEC3B copy number status was significantly associated with nodal status (P = 0.041), but not with age, menopausal status, tumor size, tumor grade, tumor histology, ER, PR and HER2 status, and adjuvant systemic therapy." (PMID 27552096, 2016). "The heterogeneous population resulting from moderately elevated APOBEC3B expression may then yield more aggressive and drug resisting tumor cells that result in poor clinical outcomes." (PMID 25123150, 2014). "The overexpression of Apobec3b in animal models confirmed its tumor-type specificity." (PMID 25038616, 2014). "Elevated APOBEC3B expression appears to be at the transcriptional level, which, depending on the tumor environment, may be up- or down-modulated." (PMID 25123150, 2014). "In the present study, we examined whether APOBEC3B may also act as a molecule for tumor progression and metastasis in NSCLCs." (PMID 24748981, 2014). "We hypothesised that the lack of immunogenicity in APOBEC3B-expressingautochthonous tumours might be due to the subclonality of mutations, which havebeen shown to be less effective at generating effective adaptive immuneresponses." (PMID 35930804, 2022). "The lack of substantial numbers of APOBEC3B-induced mutations in thesemodels was potentially a consequence of a detrimental impact of APOBEC3B expressionduring early stages of tumour development, which is reflected by the downregulationof A3Bi expression in both KP and urethane-induced lung tumours." (PMID 35930804, 2022). "Taking the median expression level of APOBEC3B in tumor cases as the standard, we divided the tumor cases in TCGA datasets into high- and low-expression groups, and explored the relationship between the expression of APOBEC3B and the prognoses for different patients." (PMID 35918642, 2022). "Incontrast, APOBEC3B mRNA expression was detected in the KPA cell lines andtherefore we decided not to further characterise them as the expression of ahuman recombinant protein could affect the growth of transplanted tumours inimmune-competent hosts." (PMID 35930804, 2022).
tumor (continued). "As APOBEC3B is an endogenous carcinogenic mutagen by APOBEC-mediated cytidine deamination, we hypothesized that APOBEC mutation would result in the production of a tumor neoantigen and increased infiltration of T lymphocytes into intra- or peri-tumor tissues." (PMID 33925044, 2021). "Studies are currently underway to determine whether APOBEC3B-mediated mutagenesis is uniquely able to induce enhanced immunogenicity of tumor cell vaccines or whether other mutagenic compounds/processes—such as chemotherapy or radiation therapy—can have similar effects." (PMID 32034147, 2020). "However, the reported distinct APOBEC3B mRNA expression levels of the primary tumor that were largely retained or increased in the paired metastases could not solely be explained by heterogeneity." (PMID 28141868, 2017). "However, it remains uncertain whether APOBEC3B‐induced mutations accelerate tumor progression or not." (PMID 40213992, 2025). "NF-κB activation induces APOBEC3B mutagenesis and PD-L1 overexpression, while mTOR signaling enhances glycolysis and OXPHOS to fuel tumor growth." (PMID 40510156, 2025). "Staining the same TMA with an antibody that binds to APOBEC3A, APOBEC3B and APOBEC3G revealed characteristic nuclear APOBEC3B expression in tumour cells (Fig. EV4)." (PMID 39548236, 2025). "We also found that in some tumors, the expression of APOBEC3B was mainly positively correlated with the tumor’s pathological stage, but in CHOL and OV tumors, the expression of APOBEC3B was negatively correlated with pathological stage." (PMID 35918642, 2022). "In the dataset with the largest number of samples (GSE117556), RNA was extracted from FFPE tumor tissue; therefore, APOBEC3A and APOBEC3B expression levels were analyzed in different samples in GSE19246, which contains both frozen and FFPE tumor tissue." (PMID 35592333, 2022). "APOBEC3B expression and CD8+/CD3+ ratio of tumor-infiltrating lymphocytes were evaluated using immunohistochemistry." (PMID 33925044, 2021). "Accordingly, we found upregulation of APOBEC family genes (APOBEC3B, APOBEC3D and APOBECC3G) in IR type tumours compared with that in other types." (PMID 32235905, 2020). "Tumor size (P = 0.011), ER (P ≤ 0.0001), HER2 (P = 0.0013) and APOBEC3B expression (P = 0.037) were independent predictive factors for pCR in multivariate analysis." (PMID 30093965, 2018). "APOBEC3B is known to play key roles in NSCLC mutagenic process, contributing to subclonal diversification, intra-tumor heterogeneity and tumor evolution." (PMID 29695832, 2018). "However, APOBEC3B will not confer the same overt phenotype in every cell in which it is expressed; rather, the compounded effects of the somatic mutations will dictate the overall phenotype of each cell and the larger tumor." (PMID 25848704, 2015). "High genomic alterations in zesto lesions were inversely correlated with putative tumor suppressor genes (MTUS2, DLGAP3, RTN1, CRLF1, SLC12A5, and PDIA2) and positively correlated with APOBEC mutagenesis (APOBEC3C, APOBEC3G, APOBEC3B, and APOBEC3F) and hypoxia-related gene signatures." (PMID 40319462, 2025). "APOBEC3B expression does not increase tumor growth rate and fails to substantially increase clonal tumor mutational burden." (PMID 38254863, 2024). "The pentanucleotide regression finds enrichment of pyrimidines at position -2, supporting the role of the APOBEC3A enzyme rather than the APOBEC3B paralog in mutagenizing this particular tumor." (PMID 35015788, 2022). "To exploit the mutational burden generated by APOBEC3B expression without contributing to tumor evolution, we generated an APOBEC3B-modified tumor vaccine." (PMID 32034147, 2020). "The mechanism correlating tumor proliferation and APOBEC3B with chemotherapy efficacy has not been elucidated in our study and future research is required." (PMID 30093965, 2018).